HOTTIP (HOXA distal transcript antisense RNA)
Diseases named in the same sentence as HOTTIP in open-access papers (continued):
Sharing a sentence is not in itself a finding about the gene and the disease.
liver fibrosis (7 papers, 2019 to 2025). "This suggests the underlying mechanisms of HOTTIP in liver fibrosis and is predicted to provide new insights for therapeutic strategies." (PMID 32098245, 2020). "Having shown the function of HOTTIP in promoting the progression of liver fibrosis, we next explore the underlying mechanism of HOTTIP." (PMID 30548190, 2019). "A different study revealed that HOTTIP contributes to the development of liver fibrosis by increasing the amount of transforming growth factor beta receptor (TGFBR) 1 and TGFBR2, which in turn promotes HSC activation through downregulating miR-148a." (PMID 40616679, 2025). "When combined, that offers a new signaling cascade in liver fibrosis that involves HOTTIP-miR-150-SRF." (PMID 40616679, 2025). "TGFBR1 and TGFBR2 levels were increased by high levels of HOTTIP, which led to the progression of liver fibrosis." (PMID 34899344, 2021). "In conclusion, HOTTIP promotes HSCs cell proliferation and activation suggesting its possible role as a fibrogenic gene in liver fibrosis and plays a key role as a prognostic marker and novel therapeutic target." (PMID 34899344, 2021). "HOTTIP is involved in regulating the progression of mouse liver fibrosis by promoting HSC activation as a ceRNA for miR-148a and miR-150." (PMID 32098245, 2020). "Data from the present study demonstrated that HOTTIP silencing inhibits the activation and proliferation of HSCs, suggesting that HOTTIP plays a profibrogenic role in the progression of liver fibrosis." (PMID 30548190, 2019). "It is unclear, therefore, how HOTTIP functions biologically in liver fibrosis." (PMID 40616679, 2025). "I. They found that downregulation of HOTTIP attenuated CCl4-induced liver fibrosis in mice." (PMID 34899344, 2021). "Taken together, we provide a novel HOTTIP‐miR‐150‐SRF signalling cascade in liver fibrosis." (PMID 30548190, 2019). "Then we further analysed whether the alteration of HOTTIP exists in a mouse liver fibrosis model." (PMID 30548190, 2019). "However, the biological role of HOTTIP in liver fibrosis is unclear." (PMID 30548190, 2019). "Mechanistically, HOTTIP can function as a regulator of SRF expression through miR‐150 binding, which provides an intriguing approach for treating liver fibrosis." (PMID 30548190, 2019). "In summary, our experimental data suggest that HOTTIP can serve as the endogenous sponge to bind miR‐150 and then release its target SRF, thereby promoting the progression of liver fibrosis." (PMID 30548190, 2019). "Inhibition of lncRNAs (HIF1A-AS, Gm5091, and lincRNA-p21) and overexpression of lncRNAs (MALAT1, SCARNA10, Lnc-LFAR1, and HOTTIP) involved in the TGF-β signalling pathway could promote HSC activation and subsequently induce hepatic fibrosis." (PMID 32098245, 2020). "Further study showed that miR‐150 and SRF are involved in the profibrogenic effect of HOTTIP, which implies that targeting the HOTTIP‐miR‐150‐SRF axis may signify a new therapeutic application in liver fibrosis." (PMID 30548190, 2019). "Notably, high levels of HOTTIP downregulate miR-148a, increase the expression levels of the miR-148a targets TGF-beta receptor type-1 (TGFBR1) and TGF-beta receptor type-2 (TGFBR2) and thus contribute to liver fibrosis." (PMID 32098245, 2020). "However, the role of HOTTIP in liver fibrosis has not been well‐characterized." (PMID 30548190, 2019).
nasopharyngeal carcinoma (7 papers, 2019 to 2025). A carcinoma arising from the nasopharyngeal epithelium. "For example, LncRNA PVT1 enhances the sphere-forming ability of nasopharyngeal cancer CSCs, and LncRNA HOTTIP promotes tumorigenicity and spheroid formation in pancreatic CSCs, as shown by both in vitro and in vivo experiments." (PMID 41008534, 2025). "Recent studies have indicated that HOTTIP and MEG3 are associated with the initiation and progression of various types of tumors, including nasopharyngeal carcinoma (NPC)." (PMID 39049088, 2024). "•HOTTIP was highly expressed in the serum of Nasopharyngeal Carcinoma (NPC)." (PMID 39500018, 2024). "In another study in nasopharyngeal carcinoma cells (NPC), HOXA13 was downregulated due to knockdown of HOTTIP, and this subsequently led to the suppression of cell proliferation, invasion, and metastasis, and induced apoptosis." (PMID 40231344, 2025).
pancreatic ductal adenocarcinoma (7 papers, 2015 to 2025). An infiltrating adenocarcinoma that arises from the epithelial cells of the pancreas. "Meanwhile, the ncRNA circRTN4 facilitates tumor growth and hepatic metastasis in pancreatic ductal adenocarcinoma via the circRTN4-miR-497-5p-HOTTIP axis while simultaneously stbilizing RAB11FIP1 to drive epithelial-mesenchymal transition." (PMID 40384875, 2025). "HOTTIP also was shown to be upregulated in human pancreatic ductal adenocarcinoma tissues and to promote pancreatic ductal adenocarcinoma cell proliferation, migration, invasion and resistance by regulating HOXA13." (PMID 28938659, 2017). "The latest study confirms that HOTTIP/HOXA13 axis promotes pancreatic ductal adenocarcinoma (PDAC) tumorigenesis." (PMID 26356815, 2015).
head and neck squamous cell carcinoma (6 papers, 2019 to 2025). A squamous cell carcinoma that arises from any of the following anatomic sites: lip and oral cavity, nasal cavity, paranasal sinuses, pharynx, larynx, and salivary glands. "M1 macrophage-derived exosomal lncRNA HOTTIP can decrease proliferation, induce apoptosis, and enhance M1 phenotype differentiation in head and neck squamous cell carcinomas (HNSCC)." (PMID 37304135, 2023). "LncRNA HOTTIP, the key molecules in the anticancer effect from M1 macrophage-derived exosomes, regulates the polarization of circulating monocytes into the M1 phenotype to suppress head and neck squamous cell carcinoma (HNSCC) progression." (PMID 36986884, 2023). "Notably, exosomes derived from M1 macrophages, along with their key molecule lncRNA HOTTIP (distal HOXA transcript), have been shown to inhibit the progression of head and neck squamous cell carcinoma (HNSCC)." (PMID 39968497, 2025).
lung adenocarcinoma (5 papers, 2019 to 2024). A carcinoma that arises from the lung and is characterized by the presence of malignant glandular epithelial cells. "Using TCGA data and the TANRIC web tool, we found that high levels of HOTTIP were associated with shorter OS (p = 0.025) in a cohort of 91 stage I-II patients with lung adenocarcinoma." (PMID 30819158, 2019). "As demonstrated in a previous literature, HOTTIP, highly expressed in drug-resistant tissues, was able to promote the development of lung adenocarcinoma as well as to induce drug resistance." (PMID 33585440, 2020). "For example, HOTTIP was shown to be involved in the development of chemoresistance in lung adenocarcinoma by regulating the AKT signaling pathway." (PMID 32457911, 2020). "Using TANRIC and TCGA lung adenocarcinoma patients, we identified 1203 mRNAs and 61 miRNAs that significantly correlated with HOTTIP expression (p < 0.05)." (PMID 30819158, 2019).
esophageal squamous cell carcinoma (4 papers, 2016 to 2023). Esophageal squamous cell carcinoma (ESCC) is a type of esophageal carcinoma (EC) that can affect any part of the esophagus, but is usually located in the upper or middle third. "It was demonstrated that HOTTIP transcriptionally regulates HOXA13 in esophageal squamous cell carcinoma cells to promote carcinogenesis and metastasis." (PMID 36438902, 2022). "Moreover, a recent study has demonstrated that HOTTIP could act as a molecular sponge to regulate miR-30b expression in esophageal squamous cell carcinoma (ESCC), while their correlation in AS remains to be elucidated." (PMID 36964567, 2023). "In addition, HOTTIP functions as a ceRNA to bind miR-30b, which promotes HOXA13 expression in esophageal squamous cell carcinoma (ESCC)." (PMID 31575017, 2019).
acute myocardial infarction (3 papers, 2022 to 2025). Necrosis of the myocardium, as a result of interruption of the blood supply to the area. "Si-HOTTIP and miR-92a-2 mimics significantly decreased the myocardial infarct size (p < 0.05), while the inhibitory effect of si-HOTTIP was enhanced by miR-92a-2 mimics (p < 0.05)." (PMID 35044621, 2022). "In acute myocardial infarction (AMI), HOTTIP knockdown markedly promoted cardiomyocyte growth and inhibited cardiomyocyte apoptosis in vitro, and miR-92a-2 overexpression could significantly enhance the protective effect of HOTTIP knockdown against AMI through partially inhibiting c-Met expression." (PMID 40959107, 2025).
coronary artery disease (3 papers, 2020 to 2025). "Recently, the expression level of lncRNA HOTTIP was found to be upregulated in coronary artery disease (CAD) tissues than in normal arterial tissues." (PMID 33192490, 2020). "While lncRNA HOTTIP has been shown to be involved in coronary artery disorders, its precise function and mode of action in acute myocardial infarction are yet unknown." (PMID 40616679, 2025). "Although lncRNA HOTTIP has been identified to play an important role in coronary artery diseases, its role and specific mechanism in AMI remain unclear." (PMID 35044621, 2022). "Researchers found that the expression level of HOTTIP was higher in tissues affected by coronary artery disease (CAD) than in normal arterial tissues in a recent study." (PMID 40616679, 2025). "Although lncRNA HOTTIP has been identified to play crucial roles in coronary artery diseases, its effect and specific mechanism in AMI have not been reported." (PMID 35044621, 2022).
gestational diabetes mellitus (3 papers, 2022 to 2025). "HOTTIP was decreased in the liver of gestational diabetes mellitus (GDM) mice." (PMID 36555704, 2022). "Both miR-21 and lncRNA HOTTIP were discovered to be abnormally expressed in gestational diabetes mellitus and connected with a poor pregnancy outcome, which could be used as a prediction for early identification of gestational diabetes mellitus." (PMID 37745705, 2023). "Regarding gestational diabetes mellitus (GDM), a recent study showed that in GDM mice, HOTTIP levels were reduced while miR-423-5p was increased." (PMID 40616679, 2025).
leukemia (3 papers, 2022 to 2025). A malignant (clonal) hematologic disorder, involving hematopoietic stem cells and characterized by the presence of primitive or atypical myeloid or lymphoid cells in the bone marrow and the blood. "Furthermore, HOTTIP plays a role in leukemia by regulating HOXA9 mRNA and protein levels." (PMID 40616679, 2025). "Given that lncRNAs, such as HOXBLINC and HOTTIP, play an oncogenic role in specific subtypes of AML and B-ALL, these oncogenic lncRNAs become attractive targets for the treatment and diagnosis of cancers including leukemia." (PMID 39883527, 2025). "Both HOTTIP and HOTAIRM1, for example, have known roles in leukemia." (PMID 36139405, 2022). "Given that lncRNAs, such as HOTTIP and HOXBLINC, are expressed in a cell-type/AML subtype–specific fashion, targeting this class of lncRNAs may specifically eliminate homeotic oncogenic pathways and lead to the eradication of specific leukemias." (PMID 39883527, 2025). "It remains to be investigated whether HOTTIP also plays a role in NUP98 fusion oncoprotein–driven HOXA gene transcription and whether HOXBLINC and HOTTIP coordinate to promote the expression of HOX and other homeotic oncogenes, resulting in diverse leukemias." (PMID 39883527, 2025).
osteoarthritis (3 papers, 2018 to 2024). A noninflammatory degenerative joint disease occurring chiefly in older persons, characterized by degeneration of the articular cartilage, hypertrophy of bone at the margins and changes in the synovial membrane. "In the context of RA, HOTTIP has been identified as a crucial regulator lncRNA in knee Osteoarthritis (OA) pathogenesis." (PMID 38363110, 2024). "HOTTIP, which participate in the process of osteoarthritis advance and endochondral ossification, showed higher expression level in OA cartilage in comparison to normal cartilage." (PMID 30086750, 2018). "Moreover, HOTTIP was reported to control miR-663a/Fyn-related kinase axis and accelerate osteoarthritis progression." (PMID 37779916, 2023). "HOTTIP might be a potential predictive biomarker for osteoarthritis." (PMID 37779916, 2023).
renal carcinoma (3 papers, 2019 to 2024). A carcinoma arising from the epithelium of the renal parenchyma or the renal pelvis. "HOTTIP has been shown to bind EZH2 in renal carcinoma, but EZH2–HOTTIP interactions have not yet been reported in the liver." (PMID 34206504, 2021).
renal clear cell carcinoma (3 papers, 2020 to 2024). "Our previous studies have confirmed that HOTTIP is also involved in the construction of a ceRNA regulatory network in renal clear-cell carcinoma." (PMID 32983633, 2020). "We aim to investigate the expression and prognostic value of HOTTIP in clear cell renal cell carcinoma (ccRCC)." (PMID 32566641, 2020).
Sepsis (3 papers, 2024 to 2025). Sepsis is defined as life-threatening organ dysfunction caused by a dysregulated host response to infection. "They came to the conclusion that HOTTIP, perhaps because of its role in LPS-induced myocardial apoptosis and inflammation, is closely associated with the state of patients with sepsis and the emergence of cardiac dysfunction." (PMID 40616679, 2025). "In conclusion, elevated HOTTIP is a potential diagnostic biomarker of sepsis ARDS and can predict the onset of short-term mortality." (PMID 38238652, 2024). "At the same time, HOTTIP levels have some precision in diagnosing sepsis patients who develop ARDS from sepsis patients and have the potential as a diagnostic biomarker for sepsis patients with ARDS." (PMID 38238652, 2024). "Elevated HOTTIP may be a potential diagnostic biomarker for sepsis." (PMID 38238652, 2024). "Hence, HOTTIP serves as a valuable diagnostic biomarker for ARDS identification in sepsis patients." (PMID 39201697, 2024). "miR-574-5p, a target miRNA for HOTTIP, was reduced in patients with sepsis ARDS and negatively correlated with HOTTIP." (PMID 38238652, 2024). "The ROC curves indicate that HOTTIP levels have predictive power for mortality in patients with sepsis, with an AUC of 0.806, sensitivity and specificity of 85.71% and 71.11%, respectively, at a cutoff value of 2.045." (PMID 38238652, 2024). "Consistently, HOTTIP was also found to be generally elevated in sepsis patients in our investigation." (PMID 38238652, 2024). "Serum miR-574-5p levels were negatively correlated with HOTTIP levels in patients with ARDS sepsis (P < 0.001, r = -0.624)." (PMID 38238652, 2024). "At a cut-off value of 2.01, serum HOTTIP clearly identified ARDS sepsis patients with an AUC of 0.847 (95%CI: 0.776–0.919), sensitivity and specificity of 88.57% and 72.29%, respectively." (PMID 38238652, 2024). "Further validation studies are needed to establish the clinical utility of HOTTIP as a sepsis biomarker and its potential incorporation into clinical practice guidelines." (PMID 39201697, 2024). "The clinical significance of HOTTIP in the development of ARDS in patients with sepsis was analyzed by plotting ROC curves according to HOTTIP levels in two groups." (PMID 38238652, 2024). "Although the impact of HOTTIP levels on the prognosis of patients with sepsis is currently unknown, to fill this gap, we conducted a short-term follow-up study of included patients over 28 days." (PMID 38238652, 2024). "The results suggest that the serum HOTTIP level is correlated with the severity of sepsis." (PMID 38238652, 2024). "Here, we suspect that HOTTIP may be involved in the progression of ARDS sepsis by acting on miR-574-5p and endothelial-related target genes that modulate signaling pathways, such as cell junctions." (PMID 38238652, 2024). "Finally, patients with sepsis were grouped according to mean HOTTIP levels (1.88 ± 0.55), and Kaplan-Meier curves were plotted." (PMID 38238652, 2024). "Serum HOTTIP was noticeably elevated in patients with sepsis compared to controls (P < 0.001)." (PMID 38238652, 2024). "The presence of HOTTIP serves as a diagnostic biomarker for the occurrence of ARDS, exhibits correlation with disease severity, and provides predictive value of short-term mortality in sepsis patients." (PMID 38238652, 2024). "Additionally, they demonstrated how serum HOTTIP might predict the onset of cardiac dysfunction in sepsis patients." (PMID 40616679, 2025). "The findings suggest that dysregulated HOTTIP may be involved in the progression of ARDS in sepsis." (PMID 38238652, 2024). "Spearman coefficient analysis revealed a positive correlation between serum HOTTIP levels and APACHE II scores in patients with sepsis (r = 0.6384)." (PMID 38238652, 2024). "However, the potential function of HOTTIP in sepsis-induced ARDS remains unclear." (PMID 38238652, 2024).
Sepsis (continued). "HOTTIP was persistently up-regulated in patients with ARDS sepsis than in patients without ARDS patients (P < 0.05)." (PMID 38238652, 2024). "In our study, HOTTIP levels were found to be positively related to the SOFA score and the APACHE II score, respectively, suggesting that HOTTIP may have an impact on the condition or death of a patient with sepsis." (PMID 38238652, 2024). "Furthermore, although we selected 103 overlapping genes, it is necessary to further investigate the mRNAs that act on the HOTTIP/miR-574-5p axis, which may be a key target for the treatment of ARDS in sepsis." (PMID 38238652, 2024).
atherosclerosis (2 papers, 2021 to 2024). A disease characterized by the build-up of fatty material and calcium deposition in the arterial wall resulting in partial or complete occlusion of the arterial lumen. "Elevated HOTTIP has been demonstrated in atherosclerosis and its levels are induced by pro-inflammatory TNF-α." (PMID 38238652, 2024). "In the same line, but in an atherosclerosis model it has been shown that HOTTIP regulated endothelial cell proliferation and migration by induction of B-catenin expression and modulation of c-Myc pathway." (PMID 34111710, 2021).
cholangiocarcinoma (2 papers, 2021 to 2025). A carcinoma that arises from the intrahepatic biliary tree (intrahepatic cholangiocarcinoma) or from the junction, or adjacent to the junction, of the right and left hepatic ducts (hilar cholangiocarcinoma). "Similarly, in cholangiocarcinoma, the lncRNA HOTTIP modulates sensitivity to chemotherapy through the HOTTIP/miR-637/LASP1 axis." (PMID 39757310, 2025). "However, the role of HOTTIP is not fully investigated in cholangiocarcinoma." (PMID 34290981, 2021).
Cirrhosis (2 papers, 2016 to 2021). A chronic disorder of the liver in which liver tissue becomes scarred and is partially replaced by regenerative nodules and fibrotic tissue resulting in loss of liver function. "In contrast to HOTTIP, H19 and MEG3, we found that ANRIL expression was up-regulated both in cirrhosis vs. normal liver and in HCC vs. cirrhosis, suggesting its involvement in the process of hepatocarcinogenesis from normal liver through the precancerous stage of cirrhosis." (PMID 27894309, 2016). "Recently, a study showed significantly higher expression of HOTTIP in patients with advanced‐stage HCC, old age, male gender, white race, and no cirrhosis." (PMID 34185961, 2021).
diabetes (2 papers, 2019 to 2025). "Downregulating HOTTIP can lessen the decline in visual function and apoptosis of retinal cells caused by diabetes." (PMID 40616679, 2025). "While direct studies on HOTTIP in diabetes mellitus patient populations are limited, recent research has explored HOTTIP’s involvement in diabetic complications, particularly diabetic retinopathy." (PMID 40616679, 2025). "In mice with normal islet tissues, HOTTIP was found to be increased, whereas in animals with diabetes islet tissues, it was downregulated." (PMID 40616679, 2025).